IL2 (interleukin 2)
Diseases named in the same sentence as IL2 in open-access papers (continued):
Sharing a sentence is not in itself a finding about the gene and the disease.
tumor (continued). "Although IL-2 does not act directly on dendritic cells (DCs), it can indirectly promote the expansion and activation of DCs through activation of T-cells and NK-cells, which can lead to an improvement in anti-tumor immune response." (PMID 39958351, 2025). "In addition, the TSH‐28ζ‐CAR‐T and TSH‐BBζ‐CAR‐T cells produced substantial amounts of IFNγ and IL‐2 when coculturing with TSHR‐positive tumor cells, while no cytokines were released in the coculture with WT tumor cells." (PMID 40985353, 2025). "Moreover, concomitant Treg cell expansion induced by CD25-biased IL-2cx/IC may lead to suppression of tumor-specific CD8+ T cells, particularly once the concentration of IL-2cx/IC decreases and the CD8+ T cells cannot effectively compete for circulating IL-2." (PMID 40789741, 2025). "Similarly, in bladder cancer (BCa), CAFs release EVs that promote PD‐L1 expression in tumor cells while inhibiting the proliferation of CD8+ T cells and reducing the secretion of IFN‐γ, IL‐2, and TNF‐α by CD8+ T cells, ultimately leading to immunotherapy resistance." (PMID 41164803, 2025). "We determined the extent of pulmonary edema, a frequent toxicity of clinically dosed IL-2,7 induced by treatment with Y33 IC compared with IL-2/JES6 and Control IC for 3 consecutive days at 2 μg IL-2/dose, a schedule that was found to be therapeutic in our tumor models." (PMID 40789741, 2025). "In glycerophospholipid metabolism, TCR with co-stimulatory signals and IL-2 can activate PI3K, which converts phosphatidylinositol diphosphate (PIP2) to phosphatidylinositol triphosphate (PIP3), which then promotes T-cell proliferation and anti-tumor effects through the PI3K-Akt pathway." (PMID 40696413, 2025). "Knowing that IL-2 promotes the growth and survival of specific tumor cells, it is possible that the employment of these two actives at ULDs in MIM-10’s formulation might have modulated IL-2 expression and played a role in the observed reduction in the viability of the two treated cell lines." (PMID 40430171, 2025). "For instance, it has been established that pro-inflammatory cytokines such as IL-2, IFNs, and TNF-α are possessed with a greater repute for cell-mediated immunity activation, for example, through CTL and NK cell activation which leads to tumor growth inhibition." (PMID 40309351, 2025). "In preclinical tumor and viral models, combining individual agents, such as IL-2v plus anti-PD1, was far less efficacious for disease control than single agents, such as the anti-PD1‒IL2v agent, highlighting the advantage of cis-targeting IL-2 on the right cell type in subsequent cytokine therapies." (PMID 40410571, 2025). "Interestingly, IL-2/JES6 treatment alone, but not IL-2/JES6 treatment after ICIs led to increased tumor accumulation of Treg cells." (PMID 40789741, 2025). "Other strategies that enhance T cell function, such as IL-21 supplementation to promote effector T cell growth and activity, or Treg-targeted therapies like RG6292 to deplete Tregs without disrupting IL-2 signaling in effector T cells, show promise in restoring anti-tumor immune responses." (PMID 40149640, 2025). "Notably, liposomal IL-2 was most effective in intraperitoneal tumor models, with the combination therapy showing no significant toxicity, reinforcing the potential of liposomal chemoimmunotherapy for treating metastatic and regionally spread tumors." (PMID 40143046, 2025). "The resulting hyper-activated CD8+ T cells produce IL-2, interferon (IFN)γ, tumor necrosis factor (TNF)α, and GM-CSF and efficiently lyse autologous tumor cells via recognition of the same peptides this time presented to them in the context of the tumor’s MHC class I molecules." (PMID 41374956, 2025). "FH FOLR1-CART activation was additionally confirmed by measurement of proinflammatory cytokines IL-2, IFN-γ, and TNFα detected in 1:1 co-culture supernatant collected at 24 hours with no or minimal cytokines detected in the supernatant from NT T cells co-cultured with tumor cells." (PMID 40919994, 2025).
tumor (continued). "The anti-PD-1-IL2 fusion protein is then conceived to increase the binding of IL2 mutein to PD1+ TILs, thereby enabling low toxicities due to reduced IL2 binding to its receptors in peripheral immune cells while boosting PD1+ tumor antigen-specific T cells in the TME." (PMID 40046051, 2025). "Notably, the transfer of UCB-T cells secreting IL-12 resulted in increased survival of CD19+ tumor-bearing mice (>40 days of survival vs <40 days of survival compared to controls; *P < 0.05) without a need for pretreatment (irradiation) or IL-2 support." (PMID 40191201, 2025). "LNPs can deliver cytokines (e.g., IL-2, IL-12), immune checkpoint inhibitors (e.g., anti-PD-1 or anti-CTLA-4 peptides/mRNA), or adjuvants (e.g., TLR agonists) directly to immune cells or the tumor microenvironment, enhancing the anti-tumor immune response while minimizing systemic toxicity." (PMID 41155952, 2025). "Additionally, CD8+ T cells from both tumor and non-tumor tissues demonstrated comparable capacities to produce anti-tumor cytokines upon PMA and ionomycin stimulation, including IFN-γ, TNF-α, and IL-2, despite the higher proportion of CD103N cells in the tumor tissue." (PMID 41182407, 2025). "Actually, in a preliminary experiment, CAR-T cells were administered without IL-2 support, and neither of the two CAR-T groups exhibited anti-tumor activity (data not shown), suggesting that IL-2 indeed serves a pivotal role in enhancing the in vivo survival and functionality of CAR-T cells." (PMID 41179290, 2025). "Next, the mitochondrial membrane depolarization was assessed using JC-1 staining, and we showed that Neo-2/15 rather than IL-2 could preserve the mitochondrial membrane potential of BBζ when co-cultured with tumor cells." (PMID 40025022, 2025). "Using isolated tumor tissue, we analyzed gene expression related to cytotoxicity (Perforin, Granzyme B, Granulysin, and FasL), inflammatory or chemotactic cytokines (IFN-γ, CXCL9, CXCL10, and CXCL11), and CD8+ T cell activation and proliferation (CD69, Tbx21, IL-2, and IL-12b)." (PMID 39066478, 2024). "Indeed, in tumor antigen–reactive TILs in mice, CD8+cis-targeted IL2 showed a marked ability to markedly diminish Tox expression and reduce features of exhaustion, findings that were also seen in the accompanying manuscript in human TILs (Kaptein and colleagues)." (PMID 38563906, 2024). "Interestingly, we showed that murine 20D7SL CAR-T cells effectively control tumor growth with or without IL-2 supplement, even in the highly aggressive B16 murine tumor model that does not respond to PD-1 blockade due to immune exclusion mechanisms." (PMID 38336975, 2024). "As anticipated, upon encountering tumor antigens, the tumor-specific CTLs in conjunction with LPS-RGD-Nb36-DOX were able to quickly blockade the CTLA-4/B7 axis, as seen by increased expression of CD25, CD69, and CD62L as well as increased cytokine secretion (TNF-α, IFN-γ, and IL-2)." (PMID 38824143, 2024). "Therefore, a low-dose anti-PD-1 antibody was utilized in our regime for its capacity to address the immunosuppressive tumor microenvironment as a replacement of IL-2 rather than its conventional antitumor activity." (PMID 38769543, 2024). "Furthermore, tumor regression was reported in 9 out of 15 people who had not previously received IL-2." (PMID 39712007, 2024). "ErbB2-positive tumour cells that also expressed MUC1 were specifically targeted, stimulating an ErbB2-dependent immune activation with increased production of IFN-γ that synergistically promoted a cytotoxic response, although IL-2 secretion was relatively low compared to control CAR-T cells." (PMID 39596267, 2024). "We further explored the effects of Tug1 upregulation on the tumor immune microenvironments via flow cytometry and found that CD8+ T cells significantly increased and displayed stronger activation phenotypes with more production of IFN‐γ, IL‐2, and TNF‐α in sh‐Tug1 Hepa1‐6 cell‐bearing mice." (PMID 38981064, 2024).
tumor (continued). "However, a number of aspects of IL‐2‐Fc tumor therapy have not been studied, including quantitative tumor targeting and comparison to other fusion proteins such as immunocytokines (ICKs) containing IL‐2." (PMID 38317590, 2024). "Importantly, beyond showing the benefits of specific control of CAR-T cells, the ortho-IL-2 system also confirms that the pleiotropic effects of IL-2 are not needed to induce effective anti-tumor responses." (PMID 39114660, 2024). "The ICK results show high immune organ and tumor uptake, but in contrast to 64Cu‐DOTA‐IL‐2‐Fc, the %ID/g of 64Cu‐DOTA‐ICK is higher in the blood (ICK: 13.1; IL‐2‐Fc: 6.5), liver (ICK: 19.4; IL‐2‐Fc: 9.7), spleen (ICK: 33.3; IL‐2‐Fc: 21.1), and tumor (ICK: 14.7; IL‐2‐Fc: 9.3) at 24 h postinjection." (PMID 38317590, 2024). "Therefore, we investigated the evolutionary history of cancer associated gene sequences across 384 mammalian taxa, to detect signatures of selection across categories of oncogenes (GRB2, FGL2 and CDC42), tumour suppressors (LITAF, Casp8 and BRCA2) and immune genes (IL2, CD274 and B2M)." (PMID 38773187, 2024). "Despite contrasting therapeutic mechanisms between ICK and IL‐2‐Fc and small differences between mouse tumor models, in each instance ICK and IL‐2‐Fc treatments resulted in similar tumor growth inhibition due in large part to increased IFNγ+CD8+ T cells and/or decreased Tregs in the tumor." (PMID 38317590, 2024). "Therefore, it is likely that the IL2 or ECD region of ZIP4 contains structures that can bind to other membrane proteins, thus exerting regulatory effects through them and influencing the tumor microenvironment, promoting tumor growth and metastasis." (PMID 39664563, 2024). "In addition, Rg3 could decrease the tumor volume and enhance anti-tumor T cell immunity as evidence by the upregulated expression of Granzyme B and perforin in CD8+T cells, along with elevated serum IL-2, IFN-g and TNF-a level in Rg3-treated mice." (PMID 39247194, 2024). "Nevertheless, compared with the sole use of Sor, the co-administration of PF and Sor in tumor-bearing mice significantly enhanced the infiltration of CD4+ T cells in tumor tissues, while reversing the inhibition of CD8+ T cell infiltration and reversing the IL-2 depletion induced by Sor." (PMID 38312647, 2024). "TPV/∆66R/m-IL-2/mCherry and TPV/∆66R/m-CCL-2/mCherry virotherapy in immune-reconstituted animals demonstrated similar trends over the course of the study, with the results from both recombinants showing less overall regression in tumor volume compared to control." (PMID 39200298, 2024). "Additionally, while the increased expression of IL-2 and IFN-γ facilitate the maturation and differentiation of immune cells, IFN-γ may also lead to PD-L1 expression in tumor cells, thereby leading to immune escape." (PMID 38312647, 2024). "Enrichment in MTORC1, MYC, and UPR in the GSEA results in the high SIGLEC9 expression tumor group may promote proliferation and adaptive survival mechanisms, creating an environment conducive to cytokine production, such as IL-10, SDF-1α, and IL-2." (PMID 39727942, 2024). "In addition, celastrol directly binds to IL-2, disrupts the binding of IL-2 and CD25, markedly inhibits the proliferation and signaling of IL-2-dependent mouse T cells, and increases the number of CD8+ T cells, thereby inhibiting tumor growth." (PMID 39494324, 2024). "Notably, the IL2/JAK3/STAT5 axis has been reported critical for inflammatory responses, and plays key roles in immune‐related pathological processes in cancer, such as contributing to cancer‐related pain, tumor cell survival and T‐cell exhaustion." (PMID 38545256, 2024). "Conversely, IRG1 knockout (KO) in EG7 tumor cells via the CRISPR/Cas9 technique not only abolished itaconate production induced by thimerosal treatment but also markedly attenuated the IFNγ production and IL-2 promoter-driven LacZ activity in T cells co-cultured with EG7 cells." (PMID 39349845, 2024).
tumor (continued). "Consequently, elevated amounts of TNF-α, IL-2, and IFN-γ were produced by CAR-T cells treatment only in CLDN18.2-positive cancer cells, where predominant CD8+ T cells were evidenced, corroborating a persistent and highly tumor-infiltrating CAR-T therapy." (PMID 38685033, 2024). "First, they do not produce sufficient IL-2 to support their long-term proliferation and sustain their cytotoxic activity against cancer cells, so exogenous IL-2 must be used to achieve effective tumor cell eradication." (PMID 39850899, 2024). "Previously, we investigated the effect of IL-2 on the activation of cytotoxic lymphocytes and for the first time showed that CD4+ and CD8+ cytotoxic T lymphocytes are generated under the action of this cytokine, killing HLA-negative tumor cells via FasL-Fas interaction." (PMID 38203798, 2024). "Finally, NK cells derived from healthy donors and NB patients that were ex vivo stimulated with IL-2 and/or 562-mbIL21 stimulatory cells were injected into NB murine models, along with anti-GD2 and/or IL-2, and IL-15 before and after tumor resection." (PMID 39294470, 2024). "Cancer cells hinder the proliferation of cytotoxic T lymphocytes (CTLs) within the tumor through the production of immunosuppressive cytokines like interleukin (IL)-10, vascular endothelial growth factor (VEGF), and TGF-β, and by consuming IL-2, a critical cytokine for CTL function." (PMID 38730572, 2024). "In addition to the tumor invasive role, enrichment analysis revealed the overexpressed ELF4 was involved in the immune regulation, characterized by the elevated activity of Il6/Jak/Stat3 signaling, interferon alpha (IFN-α) response, and IL2/Stat5 signaling." (PMID 39132148, 2024). "Finally, our kinetics study revealed, for the first time to our knowledge, that by sequestering and consuming IL-2, intratumoral Tregs hindered CD8+ TIL hyperactivation in the early phase of tumor growth and promoted TOX-dependent CD8+ TIL exhaustion during tumor progression." (PMID 38787791, 2024). "In contrast, IL-2 expression exhibited a negative correlation with M0 macrophages, suggesting that IL-2 may play a role in promoting the migration of T cells, NK cells, B cells, and dendritic cells within the tumor microenvironment." (PMID 38554155, 2024). "This enhancement is further characterized by increased production of interferon-gamma (IFN-γ) and interleukin-2 (IL-2) within the TME, concurrent with downregulation of tumor necrosis factor-alpha (TNF-α) and interleukin-10 (IL-10), thereby fortifying the host’s anti-tumor defenses." (PMID 38930435, 2024). "In this respect, it will be interesting to examine whether IL-2 and IL-15 have an effect on NKG2D and CD158a-b in MAIT cells, because the cytokines enhance NKG2D expression in different lymphocytes and appear to increase the anti-tumor potential of NK cells." (PMID 38255242, 2024). "The EpCAM BiTE molecule effectively formed a binding interaction between EpCAM-positive tumor cells and CD3ε receptors on T cells, subsequently initiating the activation of naive T cells and the subsequent release of various pro-inflammatory factors, including IFN-γ, IL2, IL6, and IL10." (PMID 38464532, 2024). "Administration of T cell growth factor IL-2 and PD-1/PD-L1 blockade may achieve the dual purpose of modifying the T cell exhaustion program and yield better effector T cells from TSCM cells after the transfer, resulting in complete tumor remission." (PMID 38049832, 2023). "Unlike IL2-F8-TNFmut, IL2-7NP2-TNFmut could not induce tumor necrosis, and only a modest tumor growth retardation was observed." (PMID 37092450, 2023). "In this regard, mAbs may effectively target tumor-favoring cytokines, for example, TGF-β and IL-2." (PMID 36816749, 2023). "As a result, tumor regression was observed in 9 out of 15 patients who had not previously been received IL-2 and in 2 of 5 patients who were previously unsuccessfully treated with IL-2." (PMID 36768737, 2023).
tumor (continued). "Furthermore, IL-2/IL-2R signaling plays a critical role in neutrophil activity within the TME, modulating their recruitment, activation, and lifespan, thereby influencing tumor progression." (PMID 37516849, 2023). "Rechallenged mice showed improved survival (one mouse again achieved complete remission) and had higher numbers of tumor-specific (anti-Trp1) CD8+ T cells compared with mice receiving a primary challenge, showing modest evidence of immunologic memory consistent with other IL-2 based therapeutics." (PMID 36316485, 2023). "When the dissociated tumors of hu-BLT mice were used as targets for primary IL-2 activated NK cells in Cr-release assay, tumors from sNK cells alone or sNK cells combined with CDDP treated mice were killed much less when compared to untreated tumor-bearing mice." (PMID 37197660, 2023). "However, only PC but not Rosuvastatin Calcium has a synergistic effect with IL-2 on tumor suppression, suggesting that PC promotes anti-tumor immunity via its inhibition of MARCH5 but not HMG-CoA reductase." (PMID 37932447, 2023). "Peripherally, CD4 T cells can also secrete IL-2 and IFN-γ, which have been found to elicit M1 macrophages to inhibit tumor propagation via secretion of nitric oxide synthase (iNOS), reactive oxygen species (ROS), and IL-12, resulting in direct and indirect clearance of tumor cells." (PMID 37009485, 2023). "CoStAR significantly augmented effector function of T cells responding to T cell agonists and pMHC, enhanced tumor control in a solid cancer xenograft model, even in the absence of exogenous IL-2 support, and enhanced activity of TIL derived from multiple indications." (PMID 38022678, 2023). "However, both the toxicity and lack of tumor specificity represent a serious limitation for harnessing the engineered IL-2 forms." (PMID 36839658, 2023). "When IL-2 level decreases, it may lead to the decline of host anti-tumor immunity, which is not conducive to clearing HPV infection, and then leads to disease progression." (PMID 37256111, 2023). "Tumor cells may control the function of lymphocytes within the TME through several cytokines, such as TGF-ß and IL-2, leading to immunosuppression and tolerance, by converting the naive T cells into Treg cells, or the countering of autoimmunity, by inducing Th17 cells." (PMID 37111629, 2023). "Also, cytokines such as IL-2 and IL-6 favor tumor proliferation, inhibit apoptosis, and participate in the conversion of non-cancerous cells to tumor stem cells." (PMID 37895359, 2023). "Exploring the mechanistic basis for poor responses, we then compared the APRIL CAR to two other BCMA CARs in a series of in vitro assays, observing reduced interleukin-2 secretion and lack of sustained tumor control by APRIL CAR regardless of transduction method or co-stimulatory domain." (PMID 37399355, 2023). "In addition, only PC but not Rosuvastatin Calcium had a synergistic effect with IL-2 on tumor suppression, suggesting that PC promotes anti-tumor immunity via its inhibition of MARCH5 but not HMG-CoA reductase." (PMID 37932447, 2023). "However, FITC CAR T cells expanded in IL-7 and IL-15 rather than IL-2 did not demonstrate enhanced tumour control." (PMID 37291434, 2023). "Once the tumor volumes had reached approximately 80–100 mm3 size, PBS, non-transduced NK92 cells, NC-NKG2D-CAR-NK92 and SH-NKG2D-CAR-NK92 cells (1 × 107 cells/mouse) were injected i.v. into the tumor-bearing mice and each mouse was intraperitoneally injected with 20000 IU of IL-2." (PMID 36895027, 2023). "An expansion of Tregs was observed in the tumor with low dose IL-2, but not with intermediate or high dose IL-2, possibly owing to the fact that there is abundant expression of high-affinity IL-2 trimeric (CD25–CD122–CD132) receptors on Tregs as compared to effector T cells." (PMID 36845705, 2023).